TLR4 (toll like receptor 4)
Diseases named in the same sentence as TLR4 in open-access papers (continued):
Sharing a sentence is not in itself a finding about the gene and the disease.
Allergy (continued). "In the earlier studies, the exogenous protein of GFP and Cry1Ab/Ac could be digested without producing an allergic reaction and the TLR4 protein could be transferred to the endosome through the pathway Triad3A, Rab7b, and degenerated in the cytolysosome." (PMID 25874566, 2015). "Therefore, sustained upregulation of TLR4 in allergy may lead to pronged release of pro‐allergy factors (e.g., IL‐13 or IL‐4), rather than typical proinflammatory cytokines." (PMID 33900054, 2021). "Gene polymorphisms of TLR2-15607 (rs1898830 GG SNP) and TLR2-16934 (rs4696480 AA SNP), but not TLR4 rs4986790 and CD14 rs2569190, were involved in the protective role of maternal exposure to farming against allergy in the offspring." (PMID 30140427, 2018). "The TLR4 priming significantly increase expression of IL-6, IL-8, GM-CSF, IP-10, and RANTES in hTMSCs irrespective of allergy state, while the TLR3 priming did not significantly affect the secretion of these cytokines." (PMID 26376485, 2015). "However, the indispensability for TLR4 in HDM sensitization and allergy does not seem to be merely dependent on MD-2 mimicry for several reasons." (PMID 33424827, 2020). "MCT® is a biodegradable depot adjuvant developed primarily for use in short-course subcutaneous allergy immunotherapy (AIT), in combination with native allergens or modified allergens (allergoids) with or without Monophosphoryl Lipid A® (MPL®, a Toll-like receptor 4 agonist)." (PMID 33324411, 2020).
heart failure (80 papers, 2009 to 2026). Inability of the heart to pump blood at an adequate rate to meet tissue metabolic requirements. "A role of HSP60-induced apoptosis via TLR4 in myocyte loss in heart failure was demonstrated on rat primary isolated cardiomyocytes in vitro." (PMID 35237675, 2022). "Recently, chen with colleague reported that TLR4 activation is associated with ferroptosis in a heart failure model." (PMID 34787054, 2021). "Of note, the upregulation of TLR4 has been reported to contribute to cardiac failure and was associated with hypertension." (PMID 34230580, 2021). "Systemic administration of adrenergic agonist (Isoproterenol; ISOP) is known to facilitate cardiovascular changes associated with heart failure through an upregulation of cardiac toll-like receptor 4 (TLR4)." (PMID 28824368, 2017). "In particular, TLR4 up-regulation has been observed in human heart failure and ischemic hearts, and TLR4-deficient mice showed reduced cardiac hypertrophy following pressure overload." (PMID 21772665, 2011). "Increased activation of TLR-4 is also associated with heart failure following AMI." (PMID 37508529, 2023). "For instance, the upregulation of TLR4 causes inflammation and aggravates heart failure." (PMID 37239362, 2023). "Crude Fuzi combined with glycyrrhiza reduces the risk of heart failure by ameliorating the inflammatory response, which researchers suspect could be partly related to the inhibition of the Toll-like receptor-4 (TLR4)/NF-κB action in the heart." (PMID 37138292, 2023). "Moreover, previously we demonstrated that ICV injection of angiotensin II type 1 receptor blocker prevent LV remodeling associated with sympathoinhibition and decreased TLR4 in brainstem of MI-induced heart failure mice." (PMID 23874864, 2013). "Fu and colleagues have discovered that PAGln promotes cardiac inflammation and fibrosis in mice, thereby increasing the incidence of ventricular arrhythmias in mice with heart failure, through the activation of the TLR4/AKT/mTOR signaling pathway." (PMID 40135235, 2025). "Heart failure induces intestinal barrier dysfunction, promoting LPS translocation into the bloodstream and increasing TLR4 expression." (PMID 40640887, 2025). "Western blot analysis revealed increased TLR4 、P-IKBα/ IKBα and P-p65/p65 expressions in the heart failure group, which were significantly inhibited by TAK-242 (P < 0.05)." (PMID 40640887, 2025). "Inhibition of TLR4 has been shown to alleviate heat stroke-induced cardiomyocyte injury through inhibiting ferroptosis, while TLR4 knock-down has been found to retard ferroptosis in rats with heart failure." (PMID 38402377, 2024). "Reduced HSPB1 exacerbates mitochondrial dysfunction and inflammatory responses through the TLR4/PGC‐1α and TLR4/NFκB pathways, respectively, which eventually leads to heart failure." (PMID 38420163, 2024). "This study suggests that the prolonged oxidative stress and high levels of pyroptosis-associated proteins contribute to cardiac systolic dysfunction, suggesting TLR4 as a novel biomarker and a potential treatment target for doxorubicin-induced heart failure." (PMID 36733418, 2023). "A study showed that high-mobility groupbox 1 (HMGB1) plays a pathological role in doxorubicin-induced heart failure via TLR4." (PMID 36721803, 2023). "QSG, a traditional Chinese medicine, has been reported to inhibit the release of spleen mononuclear cells, mediate the TLR4/MyD88/NF-B network, and protect the myocardium in mice with heart failure." (PMID 37181809, 2023). "Studies have shown that the expression of TLR4 is increased in the hearts of patients with advanced heart failure and is highly correlated with cardiac inflammatory injury, while inhibition of TLR4 alleviated the progression of heart failure." (PMID 36771313, 2023). "Previous studies have reported that TLR4 is involved in promoting myocardial inflammation and ischemia/reperfusion injury, and aggravating cardiac remodeling and heart failure." (PMID 36594066, 2023).
heart failure (continued). "Of concern, TLR4 knockout slowed autophagy and ferroptosis of activated cardiomyocytes in heart failure rats." (PMID 36903542, 2023). "Knockdown of toll-like receptor 4 (TLR4) or NADPH oxidase 4 (NOX4) restrained ferroptosis and autophagy, which attenuated the loss of cardiomyocytes and delayed the progression of heart failure." (PMID 35677693, 2022). "Involvement of the Toll-like receptor 4 (TLR4) in maladaptive cardiac remodeling and heart failure (HF) upon pressure overload has been studied extensively, but less is known about the role of TLR2." (PMID 34769252, 2021). "Delineating the molecular basis of TLR4 in this critical effector pathway is needed to validate TLR4 as a potential target for cardiac inflammation and heart failure." (PMID 33159115, 2020). "Activation of TLR4 on dendritic cell (DC) is required for the induction of acute myocarditis and heart failure." (PMID 30046376, 2018). "Apart from inflammation, TLR4 is also involved in impaired cardiac function during sepsis-induced heart failure." (PMID 28690610, 2017). "Increased TLR4 expression has been reported in the myocardium from patients with heart failure and ischemia." (PMID 28690610, 2017). "This review elaborates on the emerging roles of TLR4 in myocardial inflammation, including myocarditis, MI, myocardial I/R injury, and heart failure." (PMID 27228349, 2016). "Secretion of proinflammatory cytokines as well as a known biomarker of cardiac failure such as pro BNP emphasizes the role of continuous TLR4 activation in the pathogenesis of cardiac dysfunction." (PMID 26030867, 2015). "We conclude that the expression, ligand‐binding capacity and pro‐inflammatory function of cardiomyocyte TLR4 are up‐regulated after long‐term MI, which promote inflammation and exacerbate heart failure." (PMID 26290459, 2015). "Recently, it was demonstrated that chronic brain TLR4 blockade prevented cardiac remodeling in heart failure and hypertensive rats." (PMID 25811788, 2015). "To examine these issues, in a future we should do chronic and brain-specific knockdown of TLR4 in sham and MI-induced heart failure, for example by Cre-Lox P system." (PMID 23874864, 2013). "Moreover, because TLR4 in brainstem was partially silencing in the present study, this finding suggests that partially silencing brain TLR4 causes sympathoinhibition with the prevention of LV remodeling in MI-induced heart failure through the reduction of brain proinflammatory cytokines." (PMID 23874864, 2013). "TLR4 in brainstem was significantly lower in MI-induced heart failure treated with ICV injection of TLR4-SiRNA than in that treated with ICV injection of hGAPDH-SiRNA." (PMID 23874864, 2013). "In histological analysis, infarct size was similar in MI-induced heart failure treated with TLR4-SiRNA and that treated with hGAPDH-SiRNA for 2 weeks." (PMID 23874864, 2013). "In hemodynamics data measured by Miller catheter, LV end-diastolic pressure (LVEDP) was significantly lower in MI-induced heart failure treated with TLR4-SiRNA than in that treated with hGAPDH-SiRNA." (PMID 23874864, 2013). "Gene silencing of NFκB, a downstream target for TLR4, prevents PCH and its progression to heart failure in a transgenic myotrophin model while TLR4-deficient mice are resistant to pressure overload-induced PCH and heart failure." (PMID 23638055, 2013). "The expression level of TLR4 in brainstem was significantly higher in MI-induced heart failure treated with intracerebroventricular (ICV) injection of hGAPDH-SiRNA than in sham." (PMID 23874864, 2013). "TLR4 expression in patients was about half of that detected in non-heart failure controls at all 3 time points." (PMID 24205042, 2013). "The expression of TLR4 in brainstem was significantly lower in MI-induced heart failure treated with TLR4-SiRNA than in that treated with hGAPDH-SiRNA for 2 weeks, as expected." (PMID 23874864, 2013).
heart failure (continued). "Lung weight, urinary norepinephrine excretion, and LV end-diastolic pressure were significantly lower and LV dimension was significantly smaller in MI-induced heart failure treated with TLR4-SiRNA than in that treated with hGAPDH-SiRNA for 2 weeks." (PMID 23874864, 2013). "The further examinations to clarify the upstream and downstream of brain TLR4 in MI-induced heart failure are necessary." (PMID 23874864, 2013). "The expression of TNF-α was significantly lower in MI-induced heart failure treated with TLR4-SiRNA than in that treated with hGAPDH-SiRNA for 2 weeks." (PMID 23874864, 2013). "24-hour urinary norepinephrine excretion was significantly lower in MI-induced heart failure treated with TLR4-SiRNA than in that treated with hGAPDH-SiRNA for 2 weeks." (PMID 23874864, 2013). "BW, lung, and heart weight were significantly lower in MI-induced heart failure treated with TLR4-SiRNA than in that treated with hGAPDH-SiRNA for 2 weeks." (PMID 23874864, 2013). "The expression or activation of both TLR2 and TLR4 are up-regulated in experimental models with hypertension and clinical patients with heart failure." (PMID 22808256, 2012). "Increased TLR4 expression has been observed in cardiomyocytes from human and animals with heart failure." (PMID 20202224, 2010). "The results of a number of other studies suggest that TLR4 plays an important role in maladaptive ventricular remodeling after ischemic injury or that TLR4 signaling is altered in the setting of heart failure." (PMID 20676278, 2009). "TLR-4 likely plays a key role in the pathogenesis of Graves’ Disease and may contribute to heart failure in these patients." (PMID 37508529, 2023). "Incubation with 100 μM of isoproterenol (ISO) for 6 days resulted in a dramatic induction of heart failure markers (Nppa, Nppb and Tlr4) and a significant reduction in the RBFox2 protein in cultured NRCMs, indicating cardiomyocyte dysfunction after a prolonged ISO treatment." (PMID 36674797, 2023). "This study demonstrated QSG could improve cardiac function and reduce the inflammatory response in AMI-induced HF by inhibiting splenic monocyte release and protecting myocardial function via the TLR4-MyD88-NF-κB p65 pathway in heart failure mice." (PMID 35370707, 2022). "Hence, we will further focus on the methylation levels of KRAS, IL10, TLR4 and STAT3, and further determine the risk of heart failure and patient stratification by the combination of methylation and transcriptional expression in the future." (PMID 36324504, 2022). "Interestingly, the inhibition of the TLR4/NF-κB signaling pathway reduces the expression levels of inflammatory factors, which improves cardiac function and heart failure progression." (PMID 35734399, 2022). "Overall, these data suggested that QSG could improve cardiac function and reduce the inflammatory response in AMI-induced HF by inhibiting splenic monocytes release, and protecting myocardial function via the TLR4-MyD88-NF-κB pathway in heart failure mice." (PMID 35370707, 2022). "Furthermore, in heart failure, it has been evidenced that valsartan can mitigate the inflammatory response by reducing TLR4 expression." (PMID 36061150, 2022). "However, recent studies demonstrate that in heart failure rats, TLR4 and NOX4 expression is significantly increased, autophagy and ferroptosis are enhanced, as well as the heart function is abnormal." (PMID 34513812, 2021). "The mammalian endotoxin sensor TLR4 has been shown to be associated with doxorubicin-induced cardiopathy, since no heart failure was observed in TLR4-knockout mice after doxorubicin treatment." (PMID 33668518, 2021). "Our data suggest that, reducing TLR4 mediated fibrosis and apoptosis could be a novel approach in the treatment of heart failure, keeping in the view the major role played by TLR4 in cardiac inflammation." (PMID 33159115, 2020).
heart failure (continued). "Recently, the role of circulating monocytes, which are major inflammatory cells, has been identified in the pathogenesis of heart failure through its specific signaling, which likely potentiates the cardiac inflammatory response (i.e., Toll-like receptors, or TLR4 expression)." (PMID 32397256, 2020). "Although not within the PVN, a handful of previous reports showed that systemic injection of anti-TLR4 antibody decreases serum levels of IL-6 in SHR and systemically infused TLR4 antagonist reduces serum levels of inflammatory markers in heart failure animals." (PMID 25879545, 2015). "It has been demonstrated that partially silencing brain TLR4 could prevent MI-induced LV remodeling in rats, suggested that brain TLR4 might to be a potential target of the heart failure." (PMID 26133371, 2015). "TLR4 levels were upregulated in the specimen of human heart failure and ischemic hearts." (PMID 25546437, 2014). "We previously demonstrated that TLR4 expression levels and activity (Myd88 as a marker) are increased in brainstem of MI-induced heart failure, and that blockade of brain angiotensin II type 1 receptor decreased brain TLR4 with the attenuation of LV remodeling and sympathoexcitaion." (PMID 23874864, 2013). "Partially silencing brain TLR4 by ICV injection of TLR4-SiRNA for 2 weeks could in part prevent LV remodeling with sympathoinhibition in rats with MI-induced heart failure." (PMID 23874864, 2013). "We could propose just only the potential relationship between TLR4 in brainstem, sympathetic nerve activity, and LV remodeling in MI-induced heart failure." (PMID 23874864, 2013). "The purpose of the present study was to examine whether silencing brain TLR4 could prevent LV remodeling with sympathoinhibition in MI-induced heart failure." (PMID 23874864, 2013). "In cardiac echocardiography, LV diastolic and systolic dimension (LVDD and LVDS) was significantly smaller, and LV ejection fraction (LVEF) and cardiac output were significantly higher in MI-induced heart failure treated with TLR4-SiRNA than in that treated with hGAPDH-SiRNA for 2 weeks." (PMID 23874864, 2013). "Taking all, we consider that ICV injection of TLR4-SiRNA could improve LV performance in MI-induced heart failure." (PMID 23874864, 2013). "Brain TLR4 has a potential to be a target of the treatment for MI-induced heart failure." (PMID 23874864, 2013). "Combined the previous and the present study, we could consider that brain angiotensin II type 1 receptor might exacerbate sympathoexcitation and LV remodeling through TLR4 in brainstem of MI-induced heart failure." (PMID 23874864, 2013). "At day 1 after ICV injection of TLR4-SiRNA, the expression and activity of brain TLR4 were significantly lower in MI-induced heart failure treated with TLR4-SiRNA than in that treated with hGAPDH-SiRNA, and partially silencing brain TLR4 was continued for around 4 days." (PMID 23874864, 2013). "Therapeutic strategies that block TLR2 but leave TLR4 activity intact, therefore, may provide a novel option to treat heart failure." (PMID 22808256, 2012). "Mechanistically, artesunate binds to the co-receptor MD2, allosterically inhibiting its interaction with TLR4 and thereby blocking downstream profibrotic signaling pathways, positioning artesunate as an intriguing candidate for drug repurposing in the treatment of cardiac fibrosis and heart failure." (PMID 39885144, 2025). "Because TLR4 is one of the best-characterized DAMPs receptors, and TLR4/NF-κB signaling axis plays essential roles in the pathophysiology of heart failure, we tested our hypothesis by focusing on analyzing whether loss of YAP resulted in activation of TLR4/NF-κB pathway." (PMID 34206257, 2021).